DACT2 (dishevelled binding antagonist of beta catenin 2)
Diseases named in the same sentence as DACT2 in open-access papers (continued):
Sharing a sentence is not in itself a finding about the gene and the disease.
tumor (continued). "Clinicopathological analysis revealed that HCC patients with low DACT2 expression was correlated with a larger tumor size (>5 cm) than those with high DACT2 expression." (PMID 23496880, 2013). "We demonstrate that expression of DACT2 is downregulated in HCC compared to adjacent healthy liver tissues and that reduced DACT2 expression is significantly correlated with large tumor size." (PMID 23496880, 2013). "In HCT116, HT29, and YB5 colorectal cancer cell lines, kaempferol was found to bind to DNMT1, and it significantly downregulated DACT2 methylation, upregulated expression of this tumor suppressor gene, blocked the Wnt/β-catenin signaling pathway, and inhibited tumor cell proliferation and migration." (PMID 34235089, 2021). "CACNA2D3 and DACT2 are tumor suppressor genes and epigenetic inactivation of these genes are linked with progression of various cancer types, but suppression of these genes might be identified with progression of pituitary prolactinoma." (PMID 33709028, 2021). "The influence of DACT2 on tumor cell proliferation might be mediated by its effects on the cell cycle and apoptosis." (PMID 30359298, 2018). "DACT2, one of the Dact gene family members, was shown to function as a tumor suppressor." (PMID 28796248, 2017). "Therefore, the molecular mechanisms by which DACT2 exerts the tumor-suppressor effect in HCC needs further study." (PMID 23496880, 2013). "In addition, DACT2 knockdown in MHCC97L cells also resulted in increased ability of tumor cell invasion and metastasis." (PMID 23496880, 2013). "Moreover, we identified deletions in tumor suppressors, such as DACT2 and TGFBR3." (PMID 31900418, 2020). "Therefore, we investigated whether DACT2 functions as a tumor suppressor by antagonizing Wnt/β-catenin signaling." (PMID 27708215, 2016). "SOSTDC1 and DACT2 did show prominent differential methylation in DCIS and invasive BC, but methylated WIF1 was significantly increased (P = 0.031) in DCIS tumours." (PMID 34997107, 2022). "Elevated methylation intensity of SOSTDC1, DACT2 and WIF1 was observed in patients who had advanced tumour stage, positive nodes and local or distant metastasis." (PMID 34997107, 2022). "The top downregulated genes [WIF1, DACT2, ID4, TP63, SOX10] in tumours in our transcriptomic profile were regulators of Wnt signalling, cell differentiation and morphogenesis and acted as inhibitors of tumour growth in BC31–34." (PMID 34997107, 2022). "In most patients (21/26 cases), DACT2 expression was markedly decreased in tumor tissues compared with nontumorous liver tissues." (PMID 23496880, 2013). "Only five samples showed comparable expression levels of DACT2 between tumor and noncancerous liver specimens." (PMID 23496880, 2013). "Expression of DACT2 mRNA in HCC tumor specimens was lower than in nontumoral liver specimens in 24 of the 30 paired cases." (PMID 23496880, 2013). "In the meantime, the reduced methylation status of DACT2, Wnt5A, and SFRP2 promoter was detected in TET1-CD-expressing tumor cells, with increased unmethylated sites at the promoter CpG regions, suggesting that TET1 really acts as a demethylase to renew expression of multiple TSGs in tumor cells." (PMID 30075814, 2018). "However, it was shown that promoter methylation of DACT1 and DACT2 may not be a common event in oral squamous cell carcinoma 86, suggesting promoter methylation of DACTs has the tumor cell-specific, and the precise mechanism of this gene family inactivation need to be further studied." (PMID 35864965, 2022).
cancer (17 papers, 2013 to 2025). A tumor composed of atypical neoplastic, often pleomorphic cells that invade other tissues. "In the Transwell assay including a Matrigel barrier, DACT2 overexpression was associated with significant inhibition of NPC cancer cell invasion through the Matrigel before traversing the Transwell chamber membrane (p < 0.01, p < 0.001 at 24 h)." (PMID 30359298, 2018). "Based on Evolutionary and functional conservation of Wnt signaling molecules as well as human chromosomal localization, DACT1 and DACT2 genes were predicted to be potent cancer-associated genes." (PMID 25375359, 2014). "DACT2 has also been reported to be frequently down-expressed in multiple human cancers, which suppressed the proliferation of cancer cells." (PMID 35864965, 2022). "DACT2 is repressed by promoter methylation in various cancers, including breast, colon, lung, and gastric cancers, but the mechanisms differ." (PMID 30359298, 2018). "The levels of DACT2 expression were significantly lower in cancer tissues compared to adjacent normal tissue samples (P < 0.001)." (PMID 28607412, 2017). "DACT2 was found to be involved in Wnt/β-catenin signaling in different cancers in our previous reports." (PMID 28607412, 2017). "Dapper, an antagonist of β-catenin, homolog 2 (DACT2) belongs to the DACT (Dpr/Frodo) gene family, located at 6q27, a region frequently associated with loss of heterozygosity in human cancers." (PMID 27708215, 2016). "The expression level of DACT2 was significantly reduced in cancer tissue samples compared with adjacent tissue samples (P < 0.001)." (PMID 26919254, 2016). "DACT2 is known to be depleted in many cancers, and its decreased levels closely correlate with increased occurrence, development, invasion, metastasis, and overall poor prognosis in many cancers." (PMID 39941940, 2025). "DACT2 was found frequently methylated in lung, esophageal, breast and other cancers." (PMID 32974031, 2020). "Although DACT2 was shown to regulate Wnt signaling in some carcinomas, its functions in NPC pathogenesis remain unclear." (PMID 30359298, 2018). "Low level expression of DACT2 was found in 24 cases of cancer samples, 16 of which were methylated." (PMID 28607412, 2017). "Our previous studies found DACT2 inhibits Wnt signaling in other cancers." (PMID 26919254, 2016). "DACT2 staining was observed predominantly in the cytoplasm as reported in the other cancers." (PMID 25375359, 2014).
DACT2 also shares sentences with these, for which no sentence is quoted: asthma (2 papers); RSV bronchiolitis (2); atrial fibrillation (1); benign diseases of the breast (1); bronchiolitis (1); Ductal Breast Carcinoma (1); invasive breast carcinoma (1); invasive lobular breast carcinoma (1); metastasis (1); metastatic tumors (1).